TMCC1 (transmembrane and coiled-coil domain family 1)
Description:
Endoplasmic reticulum membrane protein that promotes endoplasmic reticulum-associated endosome fission. Localizes to contact sites between the endoplasmic reticulum and endosomes and acts by promoting recruitment of the endoplasmic reticulum to endosome tubules for fission. Endosome membrane fission of early and late endosomes is essential to separate regions destined for lysosomal degradation from carriers to be recycled to the plasma membrane.
Synonyms: KIAA0779
Tractability: Antibody: UniProt predicts a signal peptide or a membrane-spanning region. PROTAC: ubiquitination databases record sites on it; its protein half-life has been measured.
Gene: Protein-coding gene on chromosome 3 (129,647,792 to 129,893,778, reverse strand). Ensembl gene ENSG00000172765.
Subcellular location: Endoplasmic reticulum membrane
Gene Ontology:
Molecular function: identical protein binding; protein binding
Biological process: endoplasmic reticulum organization; endosomal transport; endosome fission; endosome membrane tubulation; membrane fission
Cellular component: cytosol; endoplasmic reticulum membrane; endoplasmic reticulum-endosome membrane contact site; rough endoplasmic reticulum; endomembrane system
Genetic constraint (gnomAD): Loss-of-function variants: 15 observed, 53.04 expected, observed/expected ratio (o/e) 0.28, 90% interval 0.19 to 0.44. The upper end of that interval is the gene's LOEUF score, 0.44, which puts it in group 1 of 6, group 1 being the genes least tolerant of losing a copy. Missense variants: 501 observed, 842.97 expected, observed/expected ratio (o/e) 0.59, 90% interval 0.55 to 0.64. Synonymous variants: 278 observed, 318.31 expected, observed/expected ratio (o/e) 0.87, 90% interval 0.79 to 0.96.
Homologues: Orthologues: chimpanzee TMCC1 (100% identical), macaque TMCC1 (99% identical), dog TMCC1 (98% identical), pig TMCC1 (98% identical), rabbit TMCC1 (97% identical), mouse Tmcc1 (96% identical), guinea pig TMCC1 (95% identical), rat Tmcc1 (95% identical), tropical clawed frog tmcc1 (70% identical), zebrafish tmcc1b (70% identical), zebrafish TMCC1 (45% identical), Drosophila melanogaster Dmtn (34% identical), and 1 more. Paralogues in human: TMCC2 (57% identical), TMCC3 (37% identical), TEX28 (20% identical).
Diseases named in the same sentence as TMCC1 in open-access papers:
TMCC1 is named in the same sentence as 15 diseases in open-access papers, as found by Europe PMC text mining. Sharing a sentence is not in itself a finding about the gene and the disease. The quoted sentences say what the papers report.
anxiety disorder (1 paper, 2025). A category of psychiatric disorders which are characterized by anxious feelings or fear often accompanied by physical symptoms associated with anxiety. "The TMCC1, OCA2 and ADIPOR2 genes have also been identified in a recent cross-anxiety disorder EWAS." (PMID 40281224, 2025).
asthma (1 paper, 2020). "The disease–gene association p-value scores (−1og10) in moderate asthma-related genes ranged from 3.2 (ZNF862) to 6 (PER2), while in severe asthma-related genes, it varied from 2.2 (TMCC1) to 6 (SLCO1B3, and WNK4)." (PMID 32512817, 2020).
cervical adenocarcinoma (1 paper, 2020). An adenocarcinoma arising from the cervical epithelium. "A high GPER expression has been reported in cervical adenocarcinoma cell lines HeLa229, OMC4, HCA1, CAC-1, and TMCC1 and in tissue samples of cervical adenocarcinoma collected from patients." (PMID 32973677, 2020).
colon cancer (1 paper, 2022). "For colon cancer, identified biomarkers are CD15, CD104, CD324, CD326, CD49f, and for renal cancer, CD24, CD26, CD106 (VCAM1), EGFR, SSEA-3 (B3GALT5), SSEA-4 (TMCC1), TIM1 (HAVCR1), and TRA-1-60R (PODXL)." (PMID 36221114, 2022). "Ultimately, based on our MCIA, we identified CD15, CD104 (Integrin-β4), CD324 (E-cadherin), CD326 (EpCAM), and CD49f as biomarkers for colon cancer and CD24, CD26 (DPP4), CD106 (VCAM1), TIM-1, SSEA-3 (B3GALT5), SSEA-4 (TMCC1), TRA-1-60-R (PODXL) and EGFR for renal cancer." (PMID 36221114, 2022).
COVID-19 (1 paper, 2025). A disease caused by infection with severe acute respiratory syndrome coronavirus 2. "By 6 weeks post-inclusion, COVID-19 hypermethylation of genes with the highest fold-change compared to healthy controls included FAM178B, FYN, TMCC1, TMEM212-AS1, and FIG4, while the top five hypomethylated genes were GIT2, PDGFRB, SEMA6D, TNFAIP8, and ETV6." (PMID 41227320, 2025).
glioblastoma (1 paper, 2014). The most malignant astrocytic tumor (WHO grade IV). "TMCC1 protein was detected in all cell lines examined, with epithelial cells (Hep G2, Caco-2, and A549), neuroblastoma cells (SH-SY5Y), and glioblastoma cells (U87) showing high expression levels of TMCC1, and leukemia cells (HL-60 and HEL) and lymphoma cells (U-937) showing low expression levels." (PMID 24454821, 2014).
liver cancer (1 paper, 2023). An epithelial or non-epithelial malignant neoplasm that arises from the liver. "Regarding the liver cancer cell line, HepG2 exhibited the highest TMCC1 RNA level in the Cancer Cell Line Encyclopedia (CCLE); thus, HepG2 cells were selected as the cell model with a knocked-down TMCC1 gene." (PMID 37409259, 2023). "Therefore, the role of TMCC1 in liver cancer cells was investigated." (PMID 37409259, 2023). "At the protein expression level, using HCC samples and liver cancer samples from the Clinical Proteomic Tumor Analysis Consortium (CPTAC), it was further confirmed that SLC2A2 was lower expressed and TMCC1 was more highly expressed in HCC tissues." (PMID 37409259, 2023).
cancer (3 papers, 2022 to 2025). A tumor composed of atypical neoplastic, often pleomorphic cells that invade other tissues. "Machine learning identified five potential diagnostic biomarkers (COLEC12, TMCC1, CEP55, KLK3, COL4A1) with an AUC of 0.903, which are implicated in immune modulation and cancer progression." (PMID 40427030, 2025).
TMCC1 also shares sentences with these, for which no sentence is quoted: Tumor (2 papers); Facial palsy (1); glioma (1); leukemia (1); lymphoma (1); neuroblastoma (1); renal carcinoma (1).